CCNA2 (cyclin A2)
Diseases named in the same sentence as CCNA2 in open-access papers (continued):
Sharing a sentence is not in itself a finding about the gene and the disease.
follicular lymphoma (2 papers, 2013 to 2019). Follicular lymphoma is a form of non-Hodgkin lymphoma characterized by a proliferation of B cells whose nodular structure of follicular architecture is preserved. "Aggressive follicular lymphoma, a subset of NHL, is associated with upregulation of genes involved in cell cycle control such as CCNE2 (cyclin E2), CCNA2 (cyclin A2), CDK2 (cyclin-dependent kinase 2), and genes-reflecting increased metabolism and DNA synthesis." (PMID 23533401, 2013).
gastric tumor (2 papers, 2020 to 2022). "KRAS mutant gastric tumor samples (TCGA-STAD) also showed significantly higher expression of CCNA2 (p = 4.76 × 10−4 by Wilcoxon test) than wild-type gastric tumors." (PMID 32486290, 2020).
invasive ductal carcinoma (2 papers, 2009 to 2023). "Our triple-negative tumors have many of the characteristics of basal tumors: invasive ductal carcinoma, grade 3 tumors, CK5+, Vimentin+, highly proliferative markers (increased Ki-67+ and Cyclin A2+)." (PMID 37273492, 2023).
laryngeal squamous cell carcinoma (2 papers, 2006 to 2016). A squamous cell carcinoma that arises from the larynx. "In the current study, we have analyzed the expression pattern of group of genes —CCNB1, CCNB2, CCNA2, and CDK1 in laryngeal squamous cell carcinoma." (PMID 26912061, 2016). "In this study, we analyzed the expression profile of four genes (CCNA2, CCNB1, CCNB2, and CDK1) in laryngeal squamous cell carcinoma (LSCC) cell lines and tumor samples." (PMID 26912061, 2016).
malaria (2 papers, 2020 to 2022). Malaria is a serious and sometimes fatal disease caused by a parasite that commonly infects a certain type of mosquito which feeds on humans. "Furthermore, linear regression analysis identified 18 additional genes involved in cell cycle control downregulated by asymptomatic malaria, with transcription patterns correlated with CCNA2 expression." (PMID 35475529, 2022).
meningioma (2 papers, 2017 to 2024). A generally slow growing tumor attached to the dura mater. "Meningioma cells with knockdown of OGN also demonstrated significantly reduced cell proliferation and expression of the cell cycle markers cyclin A2 and cyclin B1, compared to cells with stable expression of OGN." (PMID 28923059, 2017).
Neurodegeneration (2 papers, 2016 to 2019). Progressive loss of neural cells and tissue. "Other than the potential candidate genes, the compact SPNW also included many significant connecting proteins like APP, BACE1, CCNA2, CREB1, E2F1, EGR1 and MDM2 which were previously implicated to play critical roles in many neurodegeneration disease pathogenesis including Alzheimer’s." (PMID 26784894, 2016).
prostate tumor (2 papers, 2014). "Surprisingly, gene expression of CDK7 negatively correlated to CDK2, SKP2, and CCNA2 in both GSE6919 and Singh prostate tumor datasets." (PMID 25271736, 2014). "Expression of SPDEF reduced the tumor burden, decreased the number of Ki67 and PH3-positive cells, and reduced mRNA levels of proliferation-specific genes Cdc25b, Cyclin B1, Cyclin A2, PLK1, CKS1, Aurora B and Topo2 alpha in the prostate tumors." (PMID 25254494, 2014). "Indeed, analysis of oncomine data indicated that gene expression level of SKP2, CDK2, and CCNA2 correlated positively well in both GSE6919 and Singh prostate tumor datasets." (PMID 25271736, 2014).
rectal adenocarcinomas (2 papers, 2009 to 2025). "It is interesting to observe that the effect of cyclin A2 overexpression in rectal adenocarcinomas is different from its effect in most other cancers." (PMID 20029639, 2009).
anaplastic thyroid carcinoma (1 paper, 2015). "Consistent with its role as a key cell cycle regulator, over-expression of cyclin A2 is found in many cancers, including anaplastic thyroid carcinoma." (PMID 26378658, 2015).
cardiac hypertrophy (1 paper, 2023). "Thus, we verified the expression of the fetal phenotype and atrophy-related marker Tgfb2 and the markers of cardiac hypertrophy Egr1 and Ccna2." (PMID 37108224, 2023).
chronic myelogenous leukaemia (1 paper, 2009). "Here we report that treatment of chronic myelogenous leukaemia K562 cells with doxorubicin results in an accumulation of cyclin A2 and follows by induction of apoptotic cell death." (PMID 19684852, 2009). "We have shown that reduction of cyclin A2 in human chronic myelogenous leukaemia K562 cells using small interfering RNA significantly inhibits cell proliferation, further supporting the notion that cyclin A2 can serve as a novel therapeutic target." (PMID 19684852, 2009). "In conclusion, knocking down the expression of cyclin A2 by siRNA delivered by SWNTs suppresses apoptosis and erythroid differentiation, and promotes megakaryocytic and monocyte-macrophage differentiation in human chronic myelogenous leukaemia K562 cells upon administration with DOX." (PMID 19684852, 2009).
coronary artery disease (1 paper, 2022). "At present, the relevance of CCNA2 to cardiovascular diseases, especially coronary artery disease, has not yet been reported." (PMID 35906548, 2022).
depression (1 paper, 2017). "These protein targets, especially hubs, and the functional nodes, MTOR, CDK6, SHC1, RCOR1 CCNA2 and STAT3, have been already reported to be involved in depression." (PMID 28954415, 2017).
developmental delay (1 paper, 2016). "Our model is consistent with an overall mechanistic picture that CCNA2 loss in the brain could be overcome through a developmental delay." (PMID 27425845, 2016). "The growth retardation in CCNA2-null brains corresponded to cell cycle lengthening, imposing a developmental delay." (PMID 27425845, 2016).
Immunodeficiency (1 paper, 2022). Failure of the immune system to protect the body adequately from infection, due to the absence or insufficiency of some component process or substance. "Interestingly, our study illustrated that CCNA2 could enhance the development of ccRCC via several immune-related signals, including immunodeficiency, natural killer cell-mediated cytotoxicity pathway, and IL6-JAK-STAT3 pathways." (PMID 35401923, 2022).
kidney tumors (1 paper, 2015). "Consistent with its role as a key cell cycle regulator, expression of CCNA2 was found to be elevated in a variety of tumors such as breast, cervical, liver, and kidney tumors." (PMID 26543493, 2015).
liposarcoma (1 paper, 2007). A usually painless malignant tumor that arises from adipose tissue. "Genes highly expressed in the dedifferentiated/pleomorphic liposarcomas included cell-cycle genes like CCNA2, CCNB2, CDC2, KIFC1, KIF23 and PTTG1, motility genes like AMFR, ANXA1, CKB, CNN2 and FN1 and homeostasis-related genes." (PMID 17359542, 2007).
malignant phyllodes tumor (1 paper, 2024). A phyllodes tumor with sarcomatous stroma. "Mitotic count (No./10 HPF), expression count (No./10 HPF) of Cyclin A2, Cyclin B1, Cyclin E, and PHH3, labeling indices (%) of Ki-67 and Survivin, and a maximum diameter of each benign, borderline, or malignant phyllodes tumor." (PMID 39553132, 2024).
oligodendroglioma (1 paper, 2011). A well-differentiated (WHO grade II), diffusely infiltrating neuroglial tumor, typically located in the cerebral hemispheres. "However, Cyclin A2 was more commonly amplified in the oligodendroglioma group relative the GBM group (Pearson's Chi-squared test with Yate's continuity, X2 = 12.5, df = 1, P-value = .00004)." (PMID 21660227, 2011).
rhabdoid sarcoma (1 paper, 2024). "Further supporting this interplay, loss of RB1 is a mechanism of resistance to EZH2 inhibition in rhabdoid sarcoma; upon RB1 silencing, tazemetostat no longer downregulated CCNA2." (PMID 38405800, 2024).
tongue tumors (1 paper, 2024). "Previous studies suggest that CDK1, CCNA2, and CCNB1 may be associated with inflammation, immune system disorders, and tongue tumors." (PMID 39553152, 2024).
tumor (355 papers, 1997 to 2026). "In TNBC, E2F1 is particularly implicated in promoting aggressive tumor characteristics through the upregulation of CCNA2, which regulates both the G1/S and the G2/M transition phases, and POLD2, which is crucial for DNA replication and repair." (PMID 41413688, 2025). "CCNA2 was closely associated with tumor-infiltrating immunocytes, transcription factors, and miRNAs." (PMID 40345591, 2025). "For instance, CCNA2 is pivotal in cell cycle control, with dysregulation linked to tumour development." (PMID 39795915, 2024). "Pronounced downregulation of the proliferation gene CCNA2 in 5-FU treated PDSs, was also associated with lymph node metastases as well as low tumor grade." (PMID 38124067, 2023). "In terms of 8 targets screened from Drug Repurposing Hub and CCLE datasets, it is reported that the high expression of CCNA2 is associated with a worse prognosis in PC and is correlated with advanced tumor stage." (PMID 38095640, 2023). "Further exploration led to the identification and validation of CDK1, CCNB1, AURKA, EZH2, and CCNA2, a five-gene signature with high interactions and potentially associated with tumor stemness, hypoxia enhancement, and TME regulation." (PMID 37189841, 2023). "Multidatabases were collected to evaluate the different expression, prognostic value, DNA methylation, tumor mutation burden, microsatellite instability, mismatch repair, tumor immune microenvironment, and drug sensitivity of CCNA2 across pancancer." (PMID 35401923, 2022). "Based on the character of “guilt of association” in the controlling networks in tumor, we use the transcriptome data collected from TCGA database, and the top 500 mRNAs mostly related to CCNA2 were retrieved via Spearman's correlation analysis." (PMID 35401923, 2022). "This implies that the genes were mainly expressed in the tumor cells, proving the clinical diagnostic value of CCNA2, CKAP2L, NCAPG, and NUSAP1 again." (PMID 33927744, 2021). "CCNA2 was also observed associated with sensitivity to prexasertib in the pan-cancer tumor cell line panel." (PMID 32076484, 2020). "High CCNA2 immunopositivity is associated with tumor development and poor survival rate of ESCC patients." (PMID 30766610, 2019). "The presence of high expression of cyclin A2 (in 25% or more of tumour cells) was associated with male gender (p = 0.023), more advanced T category (p = 0.003), and/or more advanced tumour stage (p = 0.002)." (PMID 29785357, 2018). "In the present study, we further discovered that the downregulation of FXR and miR-22 were highly associated with the upregulation of CCNA2 in tumor tissues relative to normal ones of HCC specimens." (PMID 27738335, 2016). "Cumulative evidences indicate that the deregulation of cyclin A2 is tightly linked to the chromosomal instability, neoplastic transformation and tumor proliferation." (PMID 19684852, 2009). "Deregulated expression of cyclin A2 seems to be closely associated with early events in tumor transformation." (PMID 19684852, 2009). "CCNA2 over-expression is frequently detected in many tumours and it has been associated with poor prognosis in different cancers." (PMID 19753302, 2009). "CCNA2's role in tumor formation suggests it might be used as a diagnostic indicator and treatment target for HCC and other types of cancer." (PMID 38895552, 2024). "The strong association of CCNA2 with tumor immunity suggests that CCNA2 may prove to be a promising therapeutic target for immunotherapy." (PMID 35401923, 2022). "CCNA2 may prove to be a new biomarker for prognostic prediction, tumor immunity assessment, and drug susceptibility evaluation in pancancer level, especially in ccRCC." (PMID 35401923, 2022). "Hyperactivation of CCNA2-CDK1 could cause abnormal replication in the early S phase, while CCNA2 deletion delays nuclear envelope breakdown and suppresses tumor formation." (PMID 35681641, 2022). "High CCNA2 expression was associated with poor overall survival (OS) and tumor stage." (PMID 34253236, 2021).
tumor (continued). "Interestingly, Ki-67 was significantly associated with the expression of cyclin A2 and cyclin B1 confirming the proliferative capacity of these tumour cells." (PMID 29785357, 2018). "We could confirm the associations of cyclin A2 with tumour size (T), nodal metastasis, and the clinical stage suggesting that high expression of cyclin A2 could be relevant for tumour progression and metastization." (PMID 29785357, 2018). "Similarly, Aiello’s study demonstrated that increased CcnA2 expression could reshape tumor-associated macrophages to promote tumor proliferation." (PMID 41323394, 2025). "In addition, evidence suggested that either miR-22 silencing or FXR knockdown reversed the diminished CCNA2 expression as well as cell proliferation inhibition caused by WA treatment and WA inhibited tumor masses in vivo in a subcutaneous xenograft mouse model of HCC." (PMID 27738335, 2016). "We also found that SE+ST animals showed increased Ccna2 gene expression and Cyclin A2 protein production in the tumor after 7 days." (PMID 41522488, 2026). "The statistical results showed that the volume of tumor xenografts in the CCNA2 knockdown group was smaller compared with that in the control group." (PMID 40345591, 2025). "Several investigations have demonstrated that CCNA2 can alter cell proliferation and differentiation by affecting various pathways, promoting tumor formation and progression and contributing to adverse pathological outcomes." (PMID 40181976, 2025). "The findings demonstrate that CCNA2, CHK1, E2F1, and TOP2A exhibit significant associations with tumor stage and size, whereas CHK2 shows a correlation solely with age." (PMID 40573296, 2025). "The correlation between CCNA2 and immune infiltration was determined in Tumor Immune Estimation Resource by immunomics." (PMID 40345591, 2025). "Western blotting results revealed that the knockdown of CCNA2 increased the expression of E-cadherin and decreased the expression of N-cadherin in tumor xenografts." (PMID 40345591, 2025). "In our study, despite the upregulation of TOP2A and CCNA2, miR-142-3p exhibited an overall tumor-suppressive phenotype, as evidenced by the inhibition of proliferation, survival, and migration pathways." (PMID 40362400, 2025). "Elevated expression of CCNA2 and CDK1—key molecules in cell cycle regulation—is strongly associated with tumor cell proliferation." (PMID 41155558, 2025). "Previous studies have shown that cyclin A2 maintains DNA replication by binding to CDK2 to form the CDK2-cyclin A2 complex, which facilitates the S/G2 phase transition and promotes tumor cell proliferation." (PMID 40699652, 2025). "Immunohistochemistry results showed that the knockdown of CCNA2 decreased the expression of ki67 and increased the expression of caspase 3 in tumor xenografts." (PMID 40345591, 2025). "Specifically, Ccna2, Kif2c, and Racgap1 primarily promote tumor cell proliferation and division by regulating the cell cycle and mitotic processes." (PMID 41323394, 2025). "Prognostic validation in HCC cohorts revealed significant overexpression of these genes in tumours, with elevated Kif2c and Ccna2 predicting poor survival." (PMID 41323394, 2025). "The statistical results showed that the weight of tumor xenografts in the CCNA2 knockdown group was smaller than that in the control group." (PMID 40345591, 2025). "Further studies in animal models are needed to validate the effects of targeting PCNA/AR interaction on tumor growth, and cyclin A2 and AR expression in tumor lesions." (PMID 40391771, 2025). "Further analysis highlighted four specific hub genes—CCNA2, CCNB2, CDK1, and TOP2A—that showed significantly higher expression in HBV‐associated HCC tumor samples compared to normal samples in the GEPIA database." (PMID 38895552, 2024). "documented that the up‐regulation of CCNA2 is correlated with an unfavourable prognosis in NSCLC and is implicated in tumour metastasis processes." (PMID 38429900, 2024).
tumor (continued). "Lastly, qRT-PCR and western blotting of tumor tissues were performed to corroborate the relative mRNA and protein expression levels of CCNA2 in the three experimental groups." (PMID 38904013, 2024). "The immunohistochemistry result of subcutaneous tumor indicated that knockdown CLSPN significantly down regulated CCNA2, CCNB1, CDK1, CDK2 and Ki67 expression." (PMID 37268895, 2023). "The promoter methylation showed that the CCNA2 gene was hypomethylated, leading to the speedy tumor progression and metastasis." (PMID 36980449, 2023). "Surprisingly, the mRNA levels of CDK1 and Cyclin A2 (CCNA2) were significantly higher in the tumor epithelial cells of EOCC tumor invasive margin compared to LOCC tumor invasive margin." (PMID 37964075, 2023). "Forthcoming studies are needed to find correlation between DNAH17‐AS1, other miRNAs and CCNA2 in this type of tumour." (PMID 37933082, 2023). "The mRNA and protein levels of cyclin A2 and cyclin B1 were increased in a tumor compared to normal samples and are promising biomarkers for the diagnosis and prognosis for CRC-suffering patients." (PMID 37316878, 2023). "Although CCNA2 is related to poor prognosis and tumor-promoting function in most tumor types, COAD is an exception." (PMID 35480884, 2022). "CCNB1 and CCNA2 are up-regulated in a variety of tumors and promote tumor proliferation, and also have a prognostic role." (PMID 35816352, 2022). "Based on the IHC results from HPA database and SMMU cohort, we validate that CCNA2 expression was more pronounced in the corresponding tumor tissues vs. normal kidney, intestine, liver, lung, breast, prostate, and brain tissues." (PMID 35401923, 2022). "IHC staining revealed that the E2A/c‐Myc and cyclin A2/CDK4 genes in the sh‐E2A tumour group were significantly downregulated, whereas the level of differentiation‐related protein CD11b was upregulated." (PMID 35001521, 2022). "The cyclin family gene CCNA2 has been shown to be tumor-promoting in multiple solid tumor types, and its expression is differential between many types of cancer and normal tissues." (PMID 36120466, 2022). "TIMER dataset indicated that CCNA2 expression was negatively correlated with tumor purity, thus enhancing infiltration of several immune cell types in ccRCC, including B cell, CD8+ T cell, CD4+ T cell, macrophage, neutrophil, and dendritic cell." (PMID 35401923, 2022). "The CCK-8 and colony formation results demonstrated that down‐regulation of CCNA2 expression inhibited U251 cell proliferation, whereas up‐regulation of CCNA2 expression promoted tumor U87 cell proliferation." (PMID 35903107, 2022). "CCNA2 has been identified as a tumor therapeutic target involved in the processes of cell proliferation." (PMID 35480884, 2022). "By comparing and analyzing the significantly down-regulated genes in dormant tumor cells with MYC_TARGETS_V1, MYC_TARGETS_V2, three significantly down-regulated genes were obtained: Ccna2, Mad2L1 and Plk1." (PMID 35305591, 2022). "Our study illustrated the correlation of expression level and genomic alternation of CCNA2 with tumor staging, progression, tumor immunity, and drug sensitivity across pancancer and subtypes, especially in ccRCC." (PMID 35401923, 2022). "IHC staining showed that the expression levels of CCNA2 mRNA and protein were low in the normal brain, lung, colon, breast, liver, and prostate but high in tumor tissues." (PMID 35401923, 2022). "Considering the involvement of CCNA2 in tumor immunity of various cancer cases, thus the dysregulation of CCNA2 will result in disorders of the cell cycle and eventually promote the pathogenesis of tumors." (PMID 36325324, 2022).